CXCL8 (C-X-C motif chemokine ligand 8)
Diseases named in the same sentence as CXCL8 in open-access papers (continued):
Sharing a sentence is not in itself a finding about the gene and the disease.
tumor (continued). "Chemokines CXCL1, CXCL2, and CXCL8 are highly expressed in Cancer Cells and act on CXCR1 and CXCR2, which are highly expressed in Neutrophil chemotactic the activity of Neutrophils and promote the generation of tumor immune microenvironment." (PMID 36401283, 2022). "Results from the phase I clinical trial demonstrated that serum CXCL8 levels were reduced, although no objective tumor response was detected." (PMID 36698392, 2022). "Silencing MGMT or ALKBH5 of GBM tumor cells could inhibit GAM infiltration and repress NEAT1 and CXCL8 expression, eventually suppressing GBM tumor cell growth and lengthening the survival of GBM patients." (PMID 35572545, 2022). "Studies have shown that activated MCs can recruit tumour-infiltrating effector T cells and natural killer cells by secreting CXCL10 and CXCL8, respectively; in addition, mast cells can also greatly alter B cell generation, development, and function by secreting cytokines such as IL-6." (PMID 35610596, 2022). "In addition, numerous mediators from EMT-induced tumors produce monocytes (CCL2) and neutrophil chemoattractants (GM-CSF, CXCL8, and GRO); the production of these mediators following the induction of EMT regulate the tumor niche immune landscape." (PMID 36091114, 2022). "Similar to CXCL1, CXCL8 expression was demonstrated in BC tumor samples where mRNA levels were independent of tumor size and stage, metastatic abundance, and chemotherapy efficacy." (PMID 36431173, 2022). "CXCL8/IL8, ENA-78/CXCL5, IL6, and TERC/CCL25, both in double co-culture and triple co-culture, indicated the formation of a microenvironment with chronic inflammation characteristic of the tumor stroma and the active participation of MSCs in these processes." (PMID 36354566, 2022). "Neutrophils infiltrate the tumor site due to IL8, MIF, and CXCL8 secretion." (PMID 35269652, 2022). "Another ligand–receptor pair, CXCL1/CXCL8/CCL2/CCL5‐ACKR1 was predicted to act between iCAFs and E1, which might regulate GC tumour progression." (PMID 35184420, 2022). "CXCL8/11/14 and VEGFA promote tumor angiogenesis in different ways." (PMID 36246978, 2022). "More and more evidences indicate that CXCL8 should be considered as a pro-tumor factor with dual roles: directly promoting tumor survival and affecting components of TME to indirectly facilitate tumor progression." (PMID 35372515, 2022). "FN1, APOA1, CXCL8, MMP1, MMP3, and THBS1 were significantly upregulated in the tumor samples." (PMID 35719376, 2022). "In addition, overexpression of CXCL8 and CXCR1 or CXCR2 led to tumor cell growth and metastasis via activating PI3K/AKT and ERK1/2 MAPK signaling." (PMID 36612163, 2022). "Furthermore, CXCR1-expressing NK cells are attracted to the TME by CXCL8 secreted by EOC cells, thus enhancing NK cell infiltration and the anti-tumor response." (PMID 35269786, 2022). "Some chemokines (CCL2, CCL5, CXCL5, CXCL8) that contribute to the development of inflammation and angiogenesis are supported by other chemokines through participation in fibrosis, HBV/HCV infections, the progression of the tumor and metastasis." (PMID 36012108, 2022). "Factors that can promote the anti-tumor neutrophil phenotype include chemokines (e.g., CXCL2, CXCL5, CXCL8, CCL2, CCL3, CCL5, CXCL12 (SDF-1), CXCL16 and IL-8) alone or together with G-CSF/GM-CSF, TNFα, IFNβ, IFNγ, IFNγ together with TNFα, Resolvin D1, hepatocyte growth factor (HGF) and IL-17." (PMID 34572138, 2021). "IL-8 is known for B-cell progression and Chemokine receptors CXCR1/2 and their ligand CXCL8 are essential for the activation and trafficking of inflammatory mediators as well as tumor progression and metastasis." (PMID 33802234, 2021). "Cellular interactions between tumor cells and endothelial, especially the CXCL1/ACKR1 and CXCL8/ACKR1 axes which may recruit ACKR1+ ECs, were enhanced in primary tumor tissues." (PMID 34185421, 2021).
tumor (continued). "In addition, they secrete chemoattractants such as CCL5, CXCL1, CXCL5, CXCL7 and CXCL8 and CXCL12, which induce migration of tumor cells to metastatic lesions." (PMID 34112253, 2021). "Likewise, CXCL8/CXCR1 and CXCL8/CXCR2 axis are known to induce tumor growth, angiogenesis, motility, and EMT." (PMID 33925575, 2021). "In addition, C/EBPδ supported the expression of the chemokines CXCL8 (IL-8) and CCL20, which are known for their tumor promoting and immunosuppressive properties." (PMID 34725321, 2021). "Furthermore, the C-X-C motif chemokine ligand (CXCL)-2, CXCL8 and CCL25 released by HCC cells can in turn increase the neutrophil ratio in the TME, forming an immunosuppressive microenvironment and leading to tumor progression." (PMID 35059434, 2021). "Finally, we discuss the effects of cycling hypoxia on the tumor microenvironment, in particular on the expression of VEGF-A, CCL2/MCP-1, CXCL1/GRO-α, CXCL8/IL-8, and COX-2 together with PGE2." (PMID 34639040, 2021). "Based on the literature database, there is no study comparing the diagnostic criteria for serum CXCL8 and CXCR2 levels with well-established tumor markers and CRP as GC biomarkers." (PMID 34680333, 2021). "Interestingly, they induce and support the formation of tumor vessels through specific secretion factors such as vascular endothelial growth factor (VEGF), transforming growth factor (TGF-β), interleukin-8 (CXCL8), and platelet-derived growth factor (PDGF)." (PMID 34281293, 2021). "The association between the COX2 and MDSCs/Treg attractants CXCL8 and CCL22, and suppressive factors IDO1 and IL-10 were observed exclusively after the BCG treatment of human BlCa tumor tissues, but not at baseline." (PMID 33809455, 2021). "Overall, these findings indicated that CXCL8 could be involved in the growth of ESCC as an autocrine/paracrine factor by increasing the migration and invasion of tumor cells." (PMID 33390169, 2021). "Using a 3D tissue culture model to represent tumour-stromal interactions, we demonstrated that HPV-negative tumour-stromal co-cultures expressed significantly higher levels of CXCL8, leading to increased neutrophil recruitment compared to their HPV-positive counterparts." (PMID 35047989, 2021). "Additionally, we reviewed the mechanisms of proinflammatory cytokines, such as C-X-C motif ligand 8 (CXCL8) and its cognate receptor, C-X-C chemokine receptor 2 (CXCR2), in contributing to tumorigenesis and tumor progression." (PMID 34640631, 2021). "The area under the ROC curve for CXCL8 was higher than those for CXCR2 and classical tumor markers." (PMID 34680333, 2021). "Angiogenesis may also be promoted by senescent MESO, which secrete elevated levels of IL‐6 and TGFβ to stimulate the expression of pro‐angiogenic CXCL1, CXCL8, HGF and VEGF by tumour cells." (PMID 34841720, 2021). "Moreover, serum levels of CXCL8, CXCR2 and classical tumor markers were higher in Lauren type 2 than in patients with Lauren type 1, while CRP concentrations were the highest in patients with Lauren type 1." (PMID 34680333, 2021). "The increase in CXCL8 expression in these tumor cells is independent of HIF-1 and nuclear factor-interleukin-6 (NF-IL-6)." (PMID 33467722, 2021). "As many of the secreted mediators from EMT-activated tumors are established chemoattractants of neutrophils (GRO, CXCL8, GM-CSF) and monocytes (CCL2), the release of these mediators upon EMT induction is poised to regulate the immune landscape of the tumor niche." (PMID 34567000, 2021). "Furthermore, inflammatory cytokines secreted in the tumor microenvironment enhance COX-2 expression and local release of prostaglandin E2 (PGE2), which boosts tumor and stromal cell expression of proangiogenic VEGF, CXCL8, and CXCL5." (PMID 34943797, 2021).
tumor (continued). "Taken together, these data suggest that rIL-1RA could be a beneficial alternative for the inhibition of tumor-dependent angiogenesis, probably by reducing the production of VEGF, CXCL8, endothelin-1, IL-1β and hepatocyte growth factor (HGF)." (PMID 35048046, 2021). "In this report, we describe a signaling pathway from PERK through C/EBPδ in cancer cells, which contributes to expression and secretion of CXCL8/IL-8 and CCL20, two chemokines that have well-documented tumor promoting effects through direct action on cancer cells as well as various immune cells." (PMID 34725321, 2021). "NPV values for CXCL8 and CXCR2 were higher in comparison to those of classical tumor markers." (PMID 34680333, 2021). "The expression of CXCL8, CXCL9, CXCL11, and CXCL13 was increased as the tumor stage increased." (PMID 33763130, 2021). "One of the most notable CXCR1/2 ligands, IL-8 (CXCL8), is a known inducer of tumor cell plasticity, attractant of suppressive myeloid-derived suppressor cells to the tumor, and correlates with failure of treatment in numerous cancer types, including failure to checkpoint inhibitor therapy." (PMID 33669155, 2021). "ELR chemokines include CXCL8, CXCL3, and CXCL1, which promote tumor angiogenesis." (PMID 32462020, 2020). "Furthermore, we identify recruitment of immunosuppressive Gr1+ myeloid cells via tumor cell expression of CXCL1, CXCL2, and CXCL8 (CXCR2 ligands) expression, which were substantially reduced with MEKi or CXCR2 blockade." (PMID 32634121, 2020). "In this setting, G-CSF operates in partnership with tumor-derived neutrophil chemoattractants, most prominently the chemokines CXCL5 (also known as epithelial neutrophil-activating peptide-78; ENA-78) and CXCL8 (IL-8)." (PMID 33233675, 2020). "Interestingly, these pathways are utilized by a series of chemokines and their receptors, such as CCL20/CCR6, CCL25/CCR9, CXCL1/CXCR2, CXCL8/CXCR1-2, CXCL12/CXCR4, and CX3CL1/CX3CR1, to inhibit apoptosis and promote tumor cell growth and proliferation." (PMID 31991604, 2020). "It was suggested that by regulation of the excess of chemokines, especially CXCL8, ACKR1 may dampen the pro-angiogenic tumor microenvironment and limit tumor metastasis." (PMID 32456359, 2020). "Moreover, CXCL12, CXCL8, or RANKL released into TME have been found capable of upregulating MMP production and breaking down ECM to induce increased tumor cell invasiveness." (PMID 32585812, 2020). "TAMs participate in the tumour angiogenesis by secreting pro‐angiogenic factors, including VEGF‐A, EGF, PlGF, TGF‐β, TNF‐α, IL‐1β, IL‐8, CCL2, CXCL8 and CXCL12, and enable tumour metastasis by up‐regulated N‐cadherin and Snail, whereas down‐regulated E‐cadherin." (PMID 32588948, 2020). "CXCL8 is an important member of the CXC chemokine family and plays an important role in the proliferation, migration, and activation of inflammatory systems in tumor cells." (PMID 32908877, 2020). "In this line, a recent study demonstrated high expression of cachexia-inducing factors, such as CXCL8, IL6, IL1B, CCL2, and TNF, in pancreatic cancer patients, whose tumor was classified as of low-purity (higher proportion of immune cells than of malignant cells)." (PMID 33604297, 2020). "Moreover, parenchymal PMN–MDSC in human renal cell cancer, have a positive correlation with IL1-β, CXCL8, CXCL5 and CCL3 and CXCR2 blockade reduced tumor weight with enhanced CD4+ and CD8+ T-cell infiltration in renal cell carcinoma-bearing mice." (PMID 32422991, 2020). "Moreover, findings presented in this paper confirm the significance of CXCL-8 in CRC progression, particularly in establishing tumor stage and distant metastases." (PMID 32192002, 2020).
tumor (continued). "Thus, TANs can produce CXCL8 and other ELR+ CXC chemokines, thereby further augmenting neutrophil migration, angiogenesis and tumor growth." (PMID 32422991, 2020). "Having analyzed associations between serum concentrations of the tested proteins and the depth of tumor invasion (T-factor) in CRC, we found that serum levels of CXCL-8 were highest in the T4 subgroup, but the differences between the subgroups (T1 + T2, T3, and T4) were not significant." (PMID 32192002, 2020). "In the total OC group, the AUC of CXCL-8 (0.8315; p < 0.001) was lower than the AUC of CRP (0.9092; p < 0.001), but higher in comparison with the AUCs of the classical tumor markers (CEA = 0.5238; p = 0.719 and SCC-Ag = 0.8250; p < 0.001) in the diagnosis of OC." (PMID 30820705, 2019). "This indicated that CXCL8 and CCL2 overexpression enhances tumor proliferation." (PMID 31788042, 2019). "PTCs displayed the highest expression of CCL20 and CXCL8 compared to normal tissues and thyroiditis, regardless of the genetic lesion beard by the tumor." (PMID 31412566, 2019). "Similarly, IL-8 (CXCL8) was the first chemokine described with pro-angiogenic properties, confirmed in several tumor types." (PMID 31297369, 2019). "CXCR1 inhibition combined with chemotherapy, results in the release of CXCL8 by dying bulk (non-CSC) tumor cells and binds with CXCR1 on the surface of BCSCs." (PMID 31788042, 2019). "In search of novel renal CSC markers, we identify an essential role for IL‐8 (CXCL8)/CXCR1 signaling in proliferation, migration, invasion, sphere formation and self‐renewal capabilities of ccRCC‐derived tumor cells, suggesting a stemness signature of this cell population." (PMID 30883740, 2019). "CXCL8 and CCL5, produced by bone marrow- and adipose-derived MSCs were prime inducers of metastasis in TNBC, acting by elevating the proliferation and invasive properties of the tumor cells, and their resistance to chemotherapy." (PMID 31031757, 2019). "In our data, the percentage of elevated concentrations (diagnostic sensitivity) and the negative predictive value (NPV) of CXCL-8 was higher than those of the classical tumor markers." (PMID 30820705, 2019). "CXCL8/IL8 signalling in endothelial cells is a potent pro-angiogenic factor, which, in concert with a vascular endothelial growth factor (VEGF), is pivotal for securing adequate blood supply to the growing tumor mass." (PMID 30126117, 2018). "CXCR1 has also been involved in tumor metastasis, as it binds CXCL6 and CXCL8." (PMID 30591657, 2018). "In addition, the ascites are rich in soluble agents that support tumor growth and tissue neovascularization, including angiogenin, VEGF, IL-6, CCL2/MCP-1, CXCL1/GRO-1, and CXCL8/IL-8." (PMID 28956065, 2018). "No conserved miR-6868-5p binding sites were identified in the 3’-UTR region of IL-8, excluding that IL-8 was directly targeted by miR-6868-5p, IL-8, also known as CXCL8, has been well documented to promote tumor angiogenesis mainly by binding to its receptor CXCR2." (PMID 30486864, 2018). "We postulate that tumor cells may acquire migratory phenotype through the IL-6/IL-6R/STAT3 axis, and potent chemokines, such as CXCL8, initiate the actual cellular movement to a specific direction." (PMID 29245982, 2017). "While NGFR-transduced cells did not respond to CXCL8, they released calcium upon stimulation with tumor supernatants, albeit 2 to 6 times less than CXCR2-transduced NK cells." (PMID 28923105, 2017). "Additionally, based on gene expression profiles, we revealed abnormalities in cytokines that have been reported to enhance tumor formation and progression (for example, CCL5, CXCL8 and CXCL12)." (PMID 28846080, 2017).
tumor (continued). "This increase in migration was dependent on the concentration of CXCL1, but not CXCL8 in the tumor supernatants." (PMID 28923105, 2017). "The finding that IFNγ inhibits the secretion of CXCL8 in BCPAP cells prompted us to evaluate whether cell migration, a well characterized CXCL8 mediated tumor-promoting activity, was also affected by IFNγ treatment." (PMID 27555670, 2016). "CXCL8 was detectable in malignant epithelium in approximately half of low-grade tumours analysed irrespective of BMI." (PMID 27241286, 2016). "In addition, relative neutrophilia enhances tumor growth and progression by activating inflammatory markers that include pro-angiogenic factors (VEGF), growth factors (CXCL8), proteases and anti-apoptotic markers (NF-kB)." (PMID 27198767, 2016). "In addition, such enhancements were accompanied by an overexpression of CXCL8/CXCR1, whose role in tumor angiogenesis and progression has been demonstrated." (PMID 26696754, 2015). "HIF-1α and CXCL8 are negative prognostic factors, biological markers of tumor invasiveness and therapeutic targets." (PMID 26078356, 2015). "Mechanically, TAMs are generally recruited from blood monocytes by diverse chemokines such as CCL2 (MCP-1), CCL5, CCL7, CXCL8 and CXCL12, migrate to diverse areas of the tumor microenvironment and differentiate according to surrounding cellular or environmental stimuli." (PMID 25685069, 2015). "In addition, CCR6/CCL20 interaction in endometrial adenocarcinoma, CXCR1/2/CXCL7 interaction in clear cell renal cell carcinoma, CXCR2/CXCL8 interaction in nasopharyngeal carcinoma, and CXCR6/CXCR16 interaction in HCC are reported to promote tumor cell growth." (PMID 25110692, 2014). "CXCR2 was proposed to be involved in the tumour malignancy via EGFR-dependent mechanism 46, while CXCL8 might play a potential role in tumour development by EGFR transactivation." (PMID 24268047, 2014). "We believe that CXCL5 and CXCL8 originated from HCC cells may be indicators of cell movement, shorter overall survival and tumour recurrence." (PMID 24268047, 2014). "In fact, CAFs release a great number of pro-angiogenic factors including VEGF, CXCL12, FGF, IL-8/CXCL8 and PDGF-C in the ECM to recruit other stromal cell types such as endothelial cells and their precursors in order to stimulate tumor angiogenesis and vasculogenesis." (PMID 24978438, 2014). "Unlike RasG12V, the over-expression of WT-Ras in the tumor cells did not induce the expression of CXCL8." (PMID 24598028, 2014). "As a result of TNFα + Estrogen + EGF stimulation, new cell subtypes have dominated the tumor cell population, expressing high levels of VLA6 and of the metastasis-related adhesion molecules CD44 and β1, accompanied by high levels of CXCL8, CCL2, and MMPs that were released by the cells." (PMID 24369447, 2013). "IL8 (or CXCL8) was originally cloned as a factor attracting and activating neutrophils, eosinophils, and T lymphocytes, and as such, it has been shown to enhance tumor angiogenesis and growth through recruitment of neutrophils to the primary tumor site." (PMID 23113900, 2012). "Another interesting example is the effects of macrophages on tumor development, which mainly depends on whether they secrete anti-tumor factors IL-12 and TNF-α, or pro-tumor factors IL-10, VEGF, PDGF, CXCL8, MMP-9 and TGF-β." (PMID 21760911, 2011). "Irrespective, the characterisation of CXCL1 and CXCR2 expression in the tumour epithelium provides a functional compensation for the absence of CXCL8." (PMID 21285972, 2011). "Notably, the chemokine IL-8 (CXCL-8) is an efficient mediator of angiogenesis and thus located at the crucial interface of inflammation and tumor biology." (PMID 18801189, 2008). "Elevated levels of the pro-angiogenic chemokine CXCL8 (IL8) have been detected in a variety of tumors, including solid EOC and EOC ascites fluid and may promote tumor growth." (PMID 16824216, 2006).